ANXA3 (annexin A3)
Diseases named in the same sentence as ANXA3 in open-access papers (continued):
Sharing a sentence is not in itself a finding about the gene and the disease.
tumor (51 papers, 2009 to 2026). "Overexpression of ANXA3 has been previously linked to tumour proliferation and metastasis in many tumours, including LC53." (PMID 38007577, 2023). "Genetic alterations in the ANXA3 gene have also been reported to be associated with an enhanced tumor susceptibility." (PMID 34355022, 2021). "We found that ANXA3 was markedly associated with Tumor size, depth of tumor infiltration (T stage), TNM stage, the local lymph node metastasis, Distant metastasis and prognosis of GC patients." (PMID 27894078, 2016). "Univariate Cox regression analysis indicated that tumor differentiation, Dukes’ stage, lymph node status and Annexin A3 expression were significantly associated with overall survival." (PMID 24260057, 2013). "These diverse functions of ANXA3 in tumors collectively indicate that ANXA3 may serve as an attractive target for novel anticancer therapies and a powerful diagnostic and prognostic biomarker for early tumor detection and population risk screening." (PMID 34355022, 2021). "ANXA3 expression was strongly associated with tumor size, stage, and poor prognosis." (PMID 29423100, 2018). "However, the underlying mechanisms of ANXA3 in promoting proliferation and metastasis of tumor cells at the molecular level need further evaluation." (PMID 28497041, 2017). "Despite the fact that interfering with ANXA3 alone could significantly inhibit tumor metastasis with and cause increased tumor growth unexpectedly in vivo, targeting ANXA3 in combination with doxorubicin therapy could inhibit tumor growth and metastasis simultaneously." (PMID 29374148, 2018). "Our study highlights that serum starvation promotes an ALIX-dependent ESCRT-III recruitment pathway, which loads protumor ANXA3 cargo to exert a profound effect on tumor progression." (PMID 42258749, 2026). "In summary, we validated five highly expressed proteins as specific targets for different tumour mutational backgrounds: CLIC3, CRABP2, and GMDS for AKT1E17K/TRAF7 tumours, CD44 for KLF4K409Q/TRAF7 tumours and ANXA3 for NF2−/− tumours." (PMID 40562609, 2025). "Proteomic analysis and validation of the NF2−/− tumours revealed that Annexin-3 (ANXA3) is over-expressed in all tumours analysed compared to AKT1E17K/TRAF7, KLF4K409Q/TRAF7 tumours, and normal meningeal tissue." (PMID 40562609, 2025). "NCH93 LUC2 NF2−/− cells engraft in NSG mice with ANXA3 KD showed reduced tumour growth after 29 days, as monitored by the IVIS imaging system compared to SCR controls." (PMID 40562609, 2025). "MT also modulates apoptosis-related proteins (e.g., Bax, Bcl-2), inhibits telomerase activity, and promotes ANXA3 expression, all of which contribute to tumor suppression." (PMID 40564074, 2025). "Validation of upregulated proteins in NF2−/− tumours revealed a markedly higher expression of Annexin-3 (ANXA3) compared to all datasets, but Solute carrier family 29 member 1 was not confirmed." (PMID 40562609, 2025). "ANXA3 KD was successfully achieved in tumour-derived primary cells, resulting in a reduction of the expression of the proliferation marker MCM2 and significantly reducing proliferation as measured by the EdU assay." (PMID 40562609, 2025). "To investigate the role of ANXA3 in low-grade NF2−/− tumours, we designed genome-integrated lentivirus knockdown (KD) constructs." (PMID 40562609, 2025). "The aberrant expression of Annexin A3 (ANXA3) promotes tumor cell proliferation, invasion, metastasis, and angiogenesis." (PMID 39728796, 2024). "Relative to the si-NC group, the si-EBLN3P group had diminished expression levels of EBLN3P and ANXA3 in nude mouse tumor tissues, decelerated tumor growing speed, reduced tumor weight, and reduced metastatic nodes in lung tissues." (PMID 37598115, 2023). "Although further studies will be needed to investigate the underlying mechanisms of these genes, it was reported that the ANXA3 gene drives tumor growth through the c-Jun N-terminal kinase (JNK) pathway." (PMID 36915208, 2023).
tumor (continued). "Aberrant expression of ANXA3 has been previously reported to promote tumor cell proliferation, invasion, metastasis, angiogenesis, and therapy resistance." (PMID 35681609, 2022). "Decreased expression of ANXA3 in PTC at both the protein (annexin A3) and mRNA levels correlates with tumor progression in sporadic PTC." (PMID 35295987, 2022). "Aberrant expression of ANXA3 promotes tumor cell proliferation, invasion, metastasis, angiogenesis, and therapy resistance to multiple chemotherapeutic drugs including platinum-based agents, fluoropyrimidines, cyclophosphamide, doxorubicin, and docetaxel." (PMID 34355022, 2021). "Over the last decade, a series of studies has identified novel clues shedding light on the functional link between ANXA3 and tumor angiogenesis." (PMID 34355022, 2021). "Many annexin family proteins, including Anxa3, have been shown to inhibit apoptosis in tumor cells due to caspase-3 and caspase-8 repression (the result of Anxa3/JNK pathway activation)." (PMID 34204832, 2021). "More recent work has also shown that ANXA3 enhances proliferation and survival of tumour cells via a Caspase‐3‐dependent mechanism." (PMID 32682335, 2020). "It is notable that, on one hand, improved tumour‐cell survival and proliferation was shown to be mediated, in part, by ANXA3‐mediated caspase 3 (CASP3) suppression." (PMID 32682335, 2020). "Annexin A3 (ANXA3) is known to play a crucial role in promoting tumor aggressiveness, impeding apoptosis and inducing pro-survival autophagy in sorafenib-resistant HCC cells." (PMID 31551425, 2019). "Overexpression of ANXA3 promotes tumor proliferation and metastasis in lung, liver, and ovarian carcinoma and is associated with chemotherapy resistance." (PMID 29374148, 2018). "ANXA3 is another cytosolic protein that exhibits an important role in tumourigenesis and metastasis; in either, its expression depends on the tumour type." (PMID 29443940, 2018). "In recent years, it has been shown that ANXA3 plays a role in a variety of tumor development processes." (PMID 29374148, 2018). "The combination of ANXA3 knockdown and doxorubicin treatment simultaneously inhibited tumor growth and metastasis in vivo." (PMID 29374148, 2018). "The ANXA3 levels in the patient samples were validated for the prognosis based on age, menopause status, tumor size, tumor node, metastasis stage, the number of lymphatic metastases, oncology grade, and molecular subtyping." (PMID 28497041, 2017). "Overexpression of ANXA3 significantly promoted tumor cell growth and increased the tumorigenic potential of a number of tumor lines in nude mice." (PMID 27894078, 2016). "The findings in this report provide proof that ANXA3 is unregulated in GC cell lines and tumor tissue samples." (PMID 27894078, 2016). "Next, we further elucidated the effect on tumor formation in vivo by downregulating Anxa3 expression." (PMID 27995049, 2016). "All of these results demonstrated that knocking down Anxa3 expression inhibited tumor formation in vivo." (PMID 27995049, 2016). "Then, the abilities of the Anxa3 knockdown cells to undergo tumor formation and metastasis in vivo were evaluated in nude mice." (PMID 27995049, 2016). "Previous studies have demonstrated that annexin family members, notably ANXA3, played a key role in tumor." (PMID 27894078, 2016). "These researches, together with ours, suggest that ANXA3 serve as a tumor oncogene in a wide range of common human tumor types." (PMID 27894078, 2016). "To further elucidate the tumor oncogene role of ANXA3 in GC, we investigated the effect of ANXA3 on the viability of GC cells in vitro." (PMID 27894078, 2016). "ANXA3 is a member of the annexin family, and important functions of ANXA3 in tumor development, metastasis, and drug resistance have been demonstrated." (PMID 26475168, 2015). "Side-by-side comparisons of CALR, ZAG, annexin A2, annexin A3 and Hp showed the different expression between tumor tissues and normal tissues." (PMID 24884814, 2014).
tumor (continued). "The expression of CALR, annexin A2, and annexin A3 in the tumor tissues was higher than that in the normal tissues." (PMID 24884814, 2014). "The data on the urine and tumor tissues obtained from UTUC patients which were discovered and verified by proteomic and immunological analysis strongly suggested that CALR, annexin A2 and annexin A3 are essential proteins secreted from UTUC tumor tissues." (PMID 24884814, 2014). "Our study also established the biomedical linkage of the critical over-expression of CALR, annexin A2 and annexin A3 between the urine and tumor tissues of UTUC patients." (PMID 24884814, 2014). "Annexin A3 expression was found to significantly correlate with tumor size and Dukes’ stage (all P<0.05)." (PMID 24260057, 2013). "Tumor size and Dukes’ stage exhibited statistically significant correlations with Annexin A3 expression." (PMID 24260057, 2013). "Independent of genetic background or tumour grade, targeting ANXA3 could be a viable therapeutic approach for treating NF2−/− tumours." (PMID 40562609, 2025). "Furthermore, the phosphorylation of ERK1/2 was evaluated in tumour-derived primary cells with ANXA3 KD, showing reduction using at least two constructs compared to the controls." (PMID 40562609, 2025). "ANXA3, which is considered an angiogenic factor, induces vascular endothelial growth factor production through the hypoxia‐inducible factor‐1 pathway and plays an important role in tumor metastasis by promoting angiogenesis." (PMID 39023413, 2024). "In addition, aberrant ANXA3 expression has also been shown to downregulate multiple pro-apoptotic proteins, promote tumor invasion and metastasis, induce angiogenesis and even regulate drug resistance in different tumor types." (PMID 36247003, 2022). "ANXA3 was also reported as an important role in a variety of tumor development processes." (PMID 35205125, 2022). "Overall, we were only able to partially confirm the observations of other authors who suggested that the ANXA3 gene may act as an oncogene and play a role in the transformation of a normal tissue into tumor, CRC invasion, and malignancy progression." (PMID 33672900, 2021). "Given that overexpression of ANXA3 has a vital impact on tumor progression, we could expect that downregulation of ANXA3 can also exert certain regulatory effects on tumorigenesis." (PMID 34355022, 2021). "Their data further indicates that targeting ANXA3 could effectively inhibit tumor growth and sensitize the response of tumor cells to sorafenib treatment." (PMID 34355022, 2021). "Moreover, western blot analysis validated the CPA-induced upregulation of ANXA3 in the isolated tumor tissues from mice that were engrafted with PC3-wt cells and subsequently exposed to a 70-day of metronomic CPA treatment." (PMID 34355022, 2021). "ANXA3 plays a relevant role in tumor metastasis, invasion, and drug treatment resistance." (PMID 33672900, 2021). "The role of ANXA3 in tumor proliferation, invasion and metastasis." (PMID 34355022, 2021). "Therefore, it is important to shedding light on the functions of ANXA3 in tumor biology in order to improve the early detection of preneoplastic tumors, to overcome anticancer therapy resistance and to develop novel, targeted approaches to treat solid tumors." (PMID 34355022, 2021). "Our findings from the present study demonstrated the up-regulation of ANXA3 in tumours from both FFS1 and FFS3 cell lines, suggesting that it may be associated with drug resistance." (PMID 29443940, 2018). "Interestingly, ANXA3 knockdown enhanced the sensitivity of the cells to Dox, which antagonized the tumor-promoting effect from the ANXA3 knockdown." (PMID 29374148, 2018). "The results showed that ANXA3 was significantly upregulated in tumor tissues." (PMID 29374148, 2018). "The in vitro studies above showed that ANXA3 knockdown could significantly inhibit cell invasion but promote tumor cell proliferation." (PMID 29374148, 2018).
tumor (continued). "Then, we stained the tumor sections for ANXA3 and Ki67 utilizing IHC staining and showed that ANXA3 was indeed downregulated in the ANXA3-knockdown group, and that ANXA3 knockdown was correlated with much higher Ki67 expression, which characterizes cell proliferation activity." (PMID 29374148, 2018). "A combination of targeting ANXA3 and chemotherapy could provide a promising therapeutic approach to inhibit tumor growth and metastasis." (PMID 29374148, 2018). "Altogether, our results suggest that targeting ANXA3 may be a promising novel treatment for tumor therapy in combination with the doxorubicin chemotherapy." (PMID 29374148, 2018). "The tumor size was monitored and measured weekly, and the results showed that ANXA3 knockdown could significantly promote tumor growth." (PMID 29374148, 2018). "Interestingly, in the cell lines in vitro and tumor nodules from nude mice in vivo, downregulating Anxa3 expression significantly decreased MMP-2 and N-cadherin expression and increased E-cadherin expression." (PMID 27995049, 2016). "Anxa3 knockdown significantly inhibited tumor formation by A549 cells in vivo; while many metastases were formed by control A549 cells, there were obvious reductions in the numbers of lung, liver, and brain metastases formed by Anxa3 knockdown in A549 cells." (PMID 27995049, 2016). "Multiple lines of evidence have indicated that Anxa3 expression might be a potential prognostic marker for tumor patients and an indicator of tumor development, invasion, and metastasis." (PMID 27995049, 2016). "Analysis of clinicopathological parameters showed that high ANXA3 expression was striking related to Tumor size (P=0.006), depth of tumor infiltration (T stage, P<0.001), TNM stage (P<0.001), and the local lymph node metastasis (N stage, P=0.023), Distant metastasis(P=0.014)." (PMID 27894078, 2016). "However, in prostatic cancer and renal cancer, it was shown that there is a relationship between Anxa3 downregulation and tumor cells development." (PMID 27995049, 2016). "Similar to annexin A2, we for the first time showed that the over-expression of annexin A3 in the urine and tumor tissues of patients with UTUC in comparison with healthy controls while annexin A3 was over-expressed in the tumor areas of eight tumor/adjacent normal tissue pairs (61.5%)." (PMID 24884814, 2014). "EBLN3P and ANXA3 might have potential roles in the diagnosis, treatment, and prognosis of OS, and this study provided a theoretical reference for further clinical research in tumor surgery." (PMID 37598115, 2023). "In addition, we also showed that ANXA3 knockdown promoted the uptake of doxorubicin, and the inhibition of ANXA3 in combination with doxorubicin could efficiently lead to blocking tumor growth as well as tumor metastasis." (PMID 29374148, 2018). "The results indicate that Annexin A3 may be involved in tumor angiogenesis by regulating HIF-1α." (PMID 24260057, 2013). "However, it has been reported that Annexin A3 may play a different role in tumor development or progression among various human organs." (PMID 24260057, 2013). "Mechanistically, ANXA3 activated the PI3K pathway and enhanced the transcription of PDGF-AA, thus promoting tumor angiogenesis." (PMID 41975188, 2026). "ANXA3 levels correlated with worse overall survival in sorafenib-treated HCC patients, and combination of anti-ANXA3 monoclonal antibody and sorafenib or regorafenib inhibited HCC tumor growth in vivo with significant increase in survival." (PMID 39682130, 2024). "In vivo experiments revealed facilitated tumor growth and metastasis in vivo fomented by EBLN3P through manipulation of HuR/ANXA3." (PMID 37598115, 2023). "As expected, xenograft nude mice transfected with si-EBLN3P displayed reduced tumor growth and weight, metastatic nodes in lung tissues, and positive expression of Ki-67, along with downregulated EBLN3P and ANXA3." (PMID 37598115, 2023).
tumor (continued). "The expression levels of ANXA2, ANXA3, ANXA4, ANXA8, and ANXA9 were significantly increased in tumor tissues compared with normal tissues." (PMID 34484309, 2021). "In contrast, Pe1 EC markers, including SLCO1A2, ANXA3, and TSC22D1, were enriched in leading edge and infiltrating tumor regions." (PMID 34228647, 2021). "They found that ANXA3 overexpression correlated with more aggressive HCC characteristics, including the presence of multiple tumor lesions, larger tumors, and advanced tumor stage and, consequently, poor prognosis of HCC patients." (PMID 31991677, 2020). "Interestingly, others’ previous findings showed that ANXA3 could simultaneously promote tumor cell proliferation and invasion in lung and liver carcinoma, but we found that ANXA3 knockdown inhibited tumor cell invasion but promoted cell proliferation both in vitro and in vivo." (PMID 29374148, 2018). "These genes are known to be implicated in proliferation (MAPK8), metastatic diffusion of tumor cells (ITGB1), drug resistance (ANXA1), coagulation (ANXA3, ANXA5) or inflammation (HPGD, NFKB1)." (PMID 29228619, 2017). "Multivariate Cox analysis was performed with the variables including tumor size, TNM stage, the number of lymphatic metastases, oncology grade, molecular subtyping, ANXA3 expression, and other indexes (all with P values < 0.10 in univariate analyses)." (PMID 28497041, 2017). "Combined the experimental data in the urine and in tumor tissues collected from patients with UTUC, the crucial over-expressed proteins are calreticulin, annexin A2, and annexin A3." (PMID 24884814, 2014). "Although ANXA3 KD affects proliferation in vitro and in vivo using higher grade cells, it seems the function of ANXA3 is not related to its expression as ANXA3 levels are reduced in grade 3 tumour tissue." (PMID 40562609, 2025). "However, overexpressing ANXA3 while silencing EBLN3P increased the tumor growth rate and weight in nude mice, the number of pulmonary metastatic nodules, and Ki-67 positive expression levels." (PMID 37598115, 2023). "For example, several components of the basement membrane (e.g., Collagens, Nidogen-1, Laminin subunit 3) were downregulated in tumor tissue, and proteins involved in Calcium-ion binding (e.g., Annexin-A3, S100A4) showed lower expression levels in tumor tissue than in tumor-adjacent tissue." (PMID 35681609, 2022). "There was no significant (P > 0.05) change in the expression of ANXA3 with respect to age, menopausal status, tumor size, and clinical stage." (PMID 28497041, 2017). "The findings positively correlated the expression of ANXA3 to lymphatic metastasis and histological grade independent of patient age, menopause status, tumor size, and clinical stage." (PMID 28497041, 2017). "Immunohistochemical results found that almost no Anxa3 expression was detected in the tumor nodules of the shAnxa3 group, which verified that the knockdown of Anxa3 was successfully maintained in vivo." (PMID 27995049, 2016). "Furthermore, Anxa3 knockdown significantly decreased MMP-2 and N-cadherin expression and increased E-cadherin expression both in cell lines in vitro and in tumor nodules examined during in vivo tumorigenesis assays." (PMID 27995049, 2016). "Even though two UTUC tumor tissues and most normal tissues did not express annexin A3, both annexin A2 and annexin A3 showed stronger expression in UTUC urine samples than those in the urine of healthy control." (PMID 24884814, 2014). "Prognosis was worse for ANXA3-positive patients with detectable CCSCs, suggesting that serum ANXA3 could stimulate and maintain the stem cell-like traits of CD133+ CTCs to promote tumor recurrence and metastasis." (PMID 30959764, 2019). "Western blotting analysis and immunohistochemistry of tumor tissues and normal tissues from patients with UTUC were carried out to further verify five possible UTUC biomarkers, including zinc-alpha-2-glycoprotein, calreticulin, annexin A2, annexin A3 and haptoglobin." (PMID 24884814, 2014).